SOX9 (SRY-box transcription factor 9)
Diseases named in the same sentence as SOX9 in open-access papers (continued):
Sharing a sentence is not in itself a finding about the gene and the disease.
lung adenocarcinoma (27 papers, 2012 to 2026). A carcinoma that arises from the lung and is characterized by the presence of malignant glandular epithelial cells. "SOX9 expression is elevated in lung adenocarcinoma, particularly those with KRAS mutations, and mediates Notch1-induced EMT." (PMID 41268614, 2026). "SOX9 was shown to be upregulated in adenocarcinoma of the lung, and its gene expression was associated with cell proliferation and lung development." (PMID 35886044, 2022). "Based on previous findings, we wondered whether the role of PC4 in mediating lung adenocarcinoma sensitivity to cisplatin is associated with SOX9." (PMID 34899911, 2021). "Recent literature suggests Sox9 may be a new hallmark for lung adenocarcinoma so this gene was also explored in this study." (PMID 30586399, 2018). "However, the clinical and functional significance of SOX9 expression has not been characterized previously in all stages of NSCLC despite the recently reported correlation between upregulation of SOX9 and lung adenocarcinoma, and its association with cancer cell growth." (PMID 22385677, 2012). "Recently, it has been reported that SOX9 plays a regulatory role in lung adenocarcinoma (LUAD) cell metastasis, but the specific mechanism remains to be explored." (PMID 37919693, 2023). "First, we found that SOX9 was elevated in cisplatin-resistant lung adenocarcinoma A549 cells (GSE108214) and nasopharyngeal carcinoma 5-8F cells (GSE135083) through GEO dataset analysis." (PMID 34899911, 2021). "Recent studies indicate a role of SOX9 in altering the progression and drug sensitivity of several types of tumors, including lung adenocarcinoma." (PMID 34899911, 2021). "SOX9 promotes tumorigenesis in lung adenocarcinoma through transcriptionally regulating forkhead box A1 (FOXA1)." (PMID 34899911, 2021). "In lung adenocarcinoma, SOX9, SLUG and CD44 are activated by the down-regulation of HDAC10 and stimulation of TGF-β, which mediates CSC-related cancer progression." (PMID 33997894, 2021). "By contrast, HDAC10 exhibits a potential TSG role by downregulating Sry-box transcription factor 9 (SOX9) in KRAS-driven lung adenocarcinoma." (PMID 33117804, 2020). "In lung adenocarcinoma, miR-124 regulates cell proliferation, migration, and invasion by directly targeting SOX9." (PMID 32873299, 2020). "In our study, we also demonstrated that ectopic expression of RMRP promoted the expression of KRAS, FMNL2 and SOX9 in lung adenocarcinoma cell, which were the direct taget gene of miR-206." (PMID 27906963, 2016). "In the case of mutations of SMARCA4 in lung adenocarcinomas (LUAD), the top ranking oncomodules include SOX-9 and transcription factors of the HSF family, which have been linked to tumorigenesis before." (PMID 27095575, 2016). "In lung adenocarcinoma, SRY-box transcription factor 9-mediated matrix stiffening correlates significantly with downregulated expression of NK cells functional markers (e.g., granulysin, killer cell lectin-like receptor subfamily D member 1), indicating compromised cytotoxic function." (PMID 41362727, 2026). "Furthermore, in lung adenocarcinoma, the transcription factor SRY-box transcription factor 9 exacerbates tumor matrix stiffening by promoting collagen synthesis, inducing functional impairment of DCs." (PMID 41362727, 2026). "In addition, the research has also found that SOX9 suppresses the tumor microenvironment in lung adenocarcinoma and is mutually exclusive with various tumor immune checkpoints." (PMID 40692865, 2025). "PC4 was an upstream regulator of SOX9 in lung adenocarcinoma." (PMID 34899911, 2021). "Finally, overexpression of SOX9 abrogated the apoptosis induced by PC4 knockdown in lung adenocarcinoma cells, suggesting that SOX9 acts as a downstream factor of PC4 in mediating cell sensitivity to cisplatin." (PMID 34899911, 2021). "In addition, our data showed that ectopic expression of RMRP promoted theexpression of KRAS, FMNL2 and SOX9 in lung adenocarcinoma cell." (PMID 27906963, 2016).
lung adenocarcinoma (continued). "Furthermore, SOX9 is essential for KRAS-driven lung adenocarcinoma progression." (PMID 41268614, 2026). "Elucidating the mechanistic interplay between SOX9 and the EGFR/KRAS pathways in lung adenocarcinoma holds promise for identifying novel therapeutic targets and developing precision medicine strategies." (PMID 41268614, 2026). "In SOX9-overexpressing lung adenocarcinoma, tumor-infiltrating T cells, particularly CD8+ T cells, exhibited elevated levels of the exhaustion marker LAG3, indicating that SOX9 promotes CD8+ T cell dysfunction and exhaustion." (PMID 41293317, 2025). "Examination of the TCGA database show that CDK9 expression is elevated in lung adenocarcinomas and high expression of CDK9, SOX2, and SOX9 correlates with poor overall survival." (PMID 34359807, 2021). "For instance, we found positive correlations between SOX9 and SATB1 with these markers in colon adenocarcinoma (COAD) and lung adenocarcinoma (LUAD), respectively." (PMID 35201514, 2021). "NICD1 was found to directly bind to the SOX9 gene promoter elements and to activate its transcription, demonstrating a molecular mechanism by which NOTCH1 drives EMT and invasion in lung adenocarcinoma cells." (PMID 26491213, 2015). "Importantly, targeting SOX9 by either small interfering RNAs (siRNAs) or microRNAs significantly reduced tumor cell proliferation and invasion, chondrogenic differentiation in human mesenchymal stem cells, or resistance to targeted therapy for lung adenocarcinoma." (PMID 26384302, 2015). "In both human lung adenocarcinoma lines (H1838 and H322 cells) and immortalized lung epithelial cells (BEAS2B), the expression of NICD1 increased SOX9 (sex determining region Y-box 9), a transcription factor promoting EMT, migration, and invasion of lung adenocarcinoma cells." (PMID 26491213, 2015). "The expression of SOX9 is significantly increased in HDAC10-depleted tumor cells, TGFβ pathway-related genes are enriched in HDAC10 knocked out tumor cells, and activation of TGFβ signaling contributes to the induction of SOX9 in HDAC10 knocked out lung adenocarcinoma cells." (PMID 36171897, 2022). "Although direct evidence regarding the interaction between SOX9 and the EGFR/KRAS pathways in lung adenocarcinoma remains limited, studies in other types of cancer suggest that SOX9 may regulate the biological behavior of lung adenocarcinoma cells through crosstalk with these signaling pathways." (PMID 41268614, 2026).
cervical carcinoma (21 papers, 2014 to 2026). A carcinoma arising from either the exocervical squamous epithelium or the endocervical glandular epithelium. "Among the module genes, SOX9 was identified as the hub gene, and its expression was associated with cervical cancer prognosis." (PMID 36003340, 2022). "Based on TCGA-CESC data, higher SOX9 expression was associated with lower survival likelihood of cervical cancer patients, as revealed by the analysis conducted by the Kaplan–Meier plotter." (PMID 35083143, 2021). "Furthermore we demonstrated that SOX9 inhibited cervical cancer cell proliferation and tumor growth, associated with transcriptional induction of p21WAF1/CIP1 (p21) by direct binding to a specific region of the p21 promoter." (PMID 26036262, 2015). "Therefore, the SOX9 gene acts as an oncogene in cervical cancer, interactive with immune infiltration of cancer-associated fibroblasts, thereby affecting the prognosis of patients with cervical cancer." (PMID 36003340, 2022). "Therefore, the SOX9 gene acts as an oncogene in CC and interacts with immune infiltration of cancer-associated fibroblasts, thereby affecting the prognosis of patients with cervical cancer." (PMID 36003340, 2022). "For cervical cancer cells, a suppressor role of SOX9 has been shown to suppress tumor growth and tumorigenicity when SOX9 is overexpressed, but in esophageal squamous cell cancer, SOX9 overexpression leads to increased proliferation and tumorigenicity." (PMID 40141294, 2025). "Conversely, SOX9 itself has been shown to play a suppressor role in cervical cancer, endometrial carcinoma, melanoma, and certain intestinal tumors." (PMID 40141294, 2025). "Compared to those in normal adjacent, immunohistochemical and real-time quantitative polymerase chain reaction (qPCR) showed that the protein and mRNA expression of SOX9 in cervical cancer were higher." (PMID 36003340, 2022). "DDP-resistant cervical cancer cells were subsequently co-transfected with si-SOX9 and miR-361-3p inhibitor, exposed to 1, 2, 4, 8, 16, or 32 μg/ml DDP, and examined for cell viability and IC50 values." (PMID 35083143, 2021). "SOX9 knockdown in DDP-resistant cervical cancer cells was achieved by transfecting small interfering RNA against SOX9 (siRNA1/2/3-SOX9)." (PMID 35083143, 2021). "It has been previously reported that SOX9 targeted and activated oncogenic genes, enhancing cervical cancer cell resistance to DDP." (PMID 35083143, 2021). "miR-361-3p inhibited SOX9 expression through binding; the effects of miR-361-3p inhibition on DDP-resistant cervical cancer cells were partially reversed by SOX9 knockdown." (PMID 35083143, 2021). "The effects of the SOX9/lncRNA ANXA2P2/miR-361-3p/SOX9 regulatory loop on cervical cancer cell growth and resistance to DDP have been demonstrated." (PMID 35083143, 2021). "SOX9 expression was elevated in DDP-resistant cervical cancer cells and tissues, and SOX9 activated ANXA2P2 transcription by binding." (PMID 35083143, 2021). "The dynamic effects of the miR-361-3p/SOX9 axis on DDP-resistant cervical cancer cells were examined." (PMID 35083143, 2021). "DDP-resistant cervical cancer cells were then co-transfected with si-SOX9 and miR-361-3p inhibitor and examined for cell phenotypes." (PMID 35083143, 2021). "SOX9 targeting oncogenic miR-130a to activate its expression and therefore affecting cervical cancer chemo-resistance to DDP through the miR-130a/CTR1 axis has been previously recognized." (PMID 35083143, 2021). "SOX9 expression was elevated in DDP-resistant cervical cancer cells and tissues, and SOX9 activated lncRNA ANXA2P2 transcription by binding." (PMID 35083143, 2021). "After confirming miR-361-3p regulation of SOX9, the dynamic effects of the miR-361-3p/SOX9 axis on cervical cancer cell resistance to DDP was subsequently investigated." (PMID 35083143, 2021).
cervical carcinoma (continued). "The G7521A variant was located at the binding site of the transcriptional repressor SOX9, a potential tumor suppressor in cervical cancer, and suppressesing cervical tumor growth through transactivating p21WAF1/CIP1." (PMID 28767682, 2017). "SOX9 is a potential tumor suppressor in cervical carcinoma, where it trans-activates p21WAF1/CIP1 and suppresses cell growth." (PMID 27457222, 2016). "We also detected the expression of SOX9 in cervical carcinoma cell lines by immunocytochemistry and Western blot." (PMID 26036262, 2015). "In our study, real-time PCR and Western blot analyses demonstrated that p21 is the only cell cycle protein that is positively regulated by SOX9 in all SOX9-modified cervical cancer cell lines, as well as in their respective tumor xenografts." (PMID 26036262, 2015). "Overexpression of SOX9 in cervical carcinoma cells (SiHa and C33A) inhibited cell growth in vitro and tumor formation in vivo." (PMID 26036262, 2015). "We suggest that SOX9 is a potential therapeutic target in cervical carcinoma, that specifically transactivates p21WAF1/CIP1." (PMID 26036262, 2015). "The densitometry analysis showed that the average level of SOX9 in normal cervical tissue was significantly higher than that in cervical carcinoma (P < 0.05)." (PMID 26036262, 2015). "In our study, a luciferase reporter assay and qChIP assay confirmed that SOX9 directly transactivated p21 through binding with the proximal agtgATTGTgatgg consensus sequence within the p21 promoter in cervical carcinoma cells." (PMID 26036262, 2015). "Here we showed that SOX9 is down-regulated in cervical cancer and represents tumor-suppressor in this malignancy." (PMID 26036262, 2015). "In the present study, SOX9 was highly expressed in the normal cervix, but gradually decreased in cervical carcinoma in situ, as well as in invasive cervical carcinomas according to semiquantitative IHC and Western blot analysis." (PMID 26036262, 2015). "The effects of SOX9 on the proliferation, viability, and tumor formation of cervical carcinoma cells were assessed through the silencing and overexpression of SOX9." (PMID 26036262, 2015). "Dysregulated activation of numerous genes, including cluster of differentiation 44 and SOX9, has been indicated in cervical cancer, however, the mechanism of its regulation in human cervical cancer cells remains elusive." (PMID 24932254, 2014). "Furthermore, SOX9 levels were found to be higher in cervical cancer cells and tissues that were resistant to cisplatin, and SOX9 promoted the transcription of lncRNA ANXA2P2 by binding to it." (PMID 41362671, 2026). "Sox9 has been observed to be both up and downregulated in various cervical cancer cell lines and may either promote or suppress tumor growth." (PMID 36016373, 2022). "The SOX9/miR-130a/CTR1 axis was reported to modulate cervical cancer cells." (PMID 36276096, 2022). "Moreover, SOX9 has been recognized as a direct target of miR-215-3p, which is involved in the tumor-suppressive role or miR-215-3p in cervical cancer cell." (PMID 35083143, 2021). "As mentioned in our previous study, SOX9 could activate the expression of oncogenic miR-130a, enhancing cervical cancer resistance to DDP through the miR-130a/CTR1 axis." (PMID 35083143, 2021). "SOX9 has been recognized as an oncogenic gene enhancing cervical cancer resistance to DDP." (PMID 35083143, 2021). "In contrast, Sox9 has been reported to be a tumour suppressor in cervical cancer." (PMID 30622340, 2019). "We also knocked down SOX9 in HeLa cells by small interfering RNA to determine whether SOX9 affected the functions of cervical carcinoma cells." (PMID 26036262, 2015). "We speculate that restoration of SOX9 is a potential strategy for the treatment of certain types of cervical carcinomas." (PMID 26036262, 2015).
cervical carcinoma (continued). "All of these results demonstrated that the expression of Ki67 was inversely correlated with the expression of SOX9 in these xenograft cervical carcinomas, which implies that that SOX9 suppresses the formation of cervical carcinomas through the inhibition of cell proliferation." (PMID 26036262, 2015). "Additionally, we detected the expression of SOX9 protein in 8 normal cervical specimens and in 8 cervical carcinoma specimens by Western blot." (PMID 26036262, 2015). "Thus SOX9 inhibits cell proliferation in cervical carcinoma cells at the G1/S phase transitionwhether the cervical carcinoma cells express SOX9 protein." (PMID 26036262, 2015). "Although methylation of the SOX9 gene was found in cervical carcinogenesis, the role of SOX9 in cervical carcinoma remains unclear." (PMID 26036262, 2015). "Moreover, SOX transcription factors such as SOX9 could also play a double-edged sword role in cervical cancer." (PMID 35465267, 2022). "All of these results consistently indicated that SOX9 expression is down-regulated in cervical carcinogenesis and supported the hypothesis that SOX9 might be a tumor suppressor in the development and progression of cervical carcinoma." (PMID 26036262, 2015). "In contrast, the same miRNA can inhibit cervical cancer proliferation and metastases by downregulating SRY-box transcription factor 9 (SOX9) expression." (PMID 39736850, 2025). "SOX9 knockdown significantly lowered the IC50 values of both cell lines, and partially reversed the effects of miR-361-3p inhibition on DDP-resistant cervical cancer cells’ response to DDP treatment." (PMID 35083143, 2021). "Collectively, SOX9, lncRNA ANXA2P2, and miR-361-3p form a regulatory loop, modulating DDP-resistant cervical cancer cell growth and response to DDP treatment." (PMID 35083143, 2021). "In DDP-resistant cervical cancer cells, ANXA2P2 knockdown upregulated miR-361-3p expression but downregulated SOX9 expression." (PMID 35083143, 2021). "The specific functions of the SOX9/lncRNA ANXA2P2/miR-361-3p/SOX9 regulatory loop on the growth and DDP-resistance of cervical cancer cells were demonstrated." (PMID 35083143, 2021). "In addition, SOX9 could inversely regulate miR-130a to affect cervical cancer chemoresistance." (PMID 30206227, 2018). "We found that HPV E6/E7-related master regulators (ENO1, FOSB, PA2G4, SOX9, TEAD4, FOXO4, and MNT) were significantly differently expressed (p < 0.001) in the cervical cancer TCGA samples (n = 306) than in normal cervix (n = 11) tissue." (PMID 28670312, 2017). "The following genes ENO1, FOSB, PA2G4, SOX9, and TEAD4 were highly expressed in cervical cancer in comparison to normal cervix (p < 0.001), while FOXO4 and MNT were significantly lower in cervical cancer (p < 0.001)." (PMID 28670312, 2017). "Consistent with the aberrant upregulation of SOX9 in DDP-resistant cervical cancer cells and tissues, SOX9 knockdown inhibited the growth of DDP-resistant cancer cells and elevated the sensitivity of DDP-resistant cervical cancer cells to DDP." (PMID 35083143, 2021). "Thus, SOX9, ANXA2P2, and miR-361-3p form a regulatory loop, modulating DDP-resistant cervical cancer cell growth and response to DDP treatment." (PMID 35083143, 2021). "Research has revealed a regulatory loop involving the SRY-box transcription factor 9 (SOX9) gene/lncRNA annexin A2 pseudogene 2 (ANXA2P2)/miR-361-3p/SOX9 regulatory axis, which impacts cell growth and resistance to the chemotherapeutic drug cisplatin in cervical cancer." (PMID 41362671, 2026). "Similar to SOX9, ANXA2P2 expression was dramatically upregulated in DDP-resistant Caski/DDP and HeLa/DDP cells compared with that in original Caski and HeLa cells, and upregulated in DDP-resistant cervical cancer tissues compared to those in non-resistant samples." (PMID 35083143, 2021).
cervical carcinoma (continued). "Differing from miR-361, SOX9 mRNA and protein expression was significantly upregulated in DDP-resistant Caski/DDP and HeLa/DDP cells compared with that in original Caski and HeLa cells, and upregulated in DDP-resistant cervical cancer tissues in comparison with non-resistant samples." (PMID 35083143, 2021).